RNU6-100P (RNA, U6 small nuclear 100, pseudogene)
Gene: Small nuclear RNA gene on chromosome 2 (64,578,892 to 64,578,997, forward strand). Ensembl gene ENSG00000252414.
Homologues: Orthologues: chimpanzee U6 (97% identical), macaque U6 (83% identical). Paralogues in human: RNU6-903P (73% identical), RNU6-959P (73% identical), RNU6-1060P (72% identical), RNU6-116P (72% identical), RNU6-1209P (72% identical), RNU6-1266P (72% identical), RNU6-12P (72% identical), RNU6-13P (72% identical), RNU6-24P (72% identical), RNU6-263P (72% identical), RNU6-32P (72% identical), RNU6-33P (72% identical), and 1285 more.